IL6 (interleukin 6)
Diseases named in the same sentence as IL6 in open-access papers (continued):
Sharing a sentence is not in itself a finding about the gene and the disease.
osteosarcoma (continued). "In this study, we demonstrated that IL-6 intervention could decrease the sensitivity of SaOS-2 and SOSP-9607 osteosarcoma cells to lobaplatin." (PMID 33791202, 2021). "In osteosarcoma cells, IL-6 produced by MSCs activates the JAK2/STAT3 signaling, with the subsequent up-regulation of multidrug resistance protein (MRP) and P-gP expression, which is relevant to poor response rates of clinical osteosarcoma chemotherapy." (PMID 34095111, 2021). "Previous studies have indicated that exogenous and autocrine IL-6 confers chemotherapeutic resistance against platinum-based drugs, which is similar to the inference from our CCK-8 and flow cytometry assay in SaOS-2 and SOSP-9607 osteosarcoma cells." (PMID 33791202, 2021). "IL-6 knockdown reduces VEGF expression and abolishes osteosarcoma-mediated angiogenesis." (PMID 34948191, 2021). "For example, IL-6 secreted by MSCs in response to paclitaxel or doxorubicin, resulted in the activation of STAT3 signaling pathway, promoting the growth of head and neck cancer, nasopharyngeal carcinomas as well as osteosarcoma." (PMID 33276524, 2020). "Furthermore, our data demonstrated that PTEN knockdown diminishes the growth-inhibitory effect and rescues the down-regulated genes, such as IL-6, PDGF8, CXCL1 and CXCL817, 18, after silencing FGD1 in osteosarcoma tumor cells." (PMID 32194840, 2020). "Furthermore, it also plays a role in angiogenesis as the IL6-induced activation of VEGF, which contributes to angiogenesis in human osteosarcoma cells, is mediated through the ASK1/p38/AP-1 pathway." (PMID 34692118, 2020). "In this study, we examined the in vitro effects of orento on the proliferation of the inflammatory cytokines interleukin (IL)-6 and IL-8, the production of type 1 collagen, and the secretion of alkaline phosphatase (ALP) in the human osteosarcoma cell line Saos-2 (Saos-2 cells)." (PMID 32992711, 2020). "Interleukin (IL)-6 and TIMP3 play important roles in the drug resistance of osteosarcoma; however, their relationship in this process remains unclear." (PMID 29731768, 2018). "Compared with these osteosarcoma cells, the human osteoblastic cell line hFOB 1.19 expressed almost no IL-6." (PMID 26623559, 2016). "Recent studies on osteosarcoma involving the LCP1 gene (also known as actin-bundling protein L-plastin or LPL), have shown that the aberrant expression of LCP1 gene activates the JAK2/STAT3 signaling pathway, linking IL-6, IL-6R, and LCP1 in the context of tumor progression." (PMID 40759647, 2025). "Experimental results showed that luteolin could inhibit cell viability and significantly decrease the expression of AKT1, STAT3, IL6, TNF, and VEGFA, and luteolin could also inhibit osteosarcoma proliferation and metastasis in osteosarcoma orthotopic mouse model." (PMID 37749554, 2023). "In addition, high levels of IL-6, but not other cytokines and chemokines, were observed in the murine osteosarcoma model." (PMID 37749554, 2023). "In a previous study using similar EI-CM samples, multi cytokine assay has identified interleukin 6 (IL-6) and leptin as molecular candidates to induce increase of osteosarcoma cell proliferation; however neither IL-6 nor leptin have been able to mimic the pro-proliferative effects of EI-CM." (PMID 31717935, 2019). "Therefore, IL-6 and TIMP3 play important roles in the drug resistance of osteosarcoma." (PMID 29731768, 2018). "Up until now, there have been no studies examining the relationship between IL6, EGFR, and STAT3 and PD-L1 using immunohistochemical expression in osteosarcoma patient subjects." (PMID 38434518, 2024). "To determine the involvement of STAT3 signaling in the anti-tumor effects of diosmetin on osteosarcoma cells, we examined the proliferation ability of Saos-2 and U2OS cells by applying diosmetin (0.3 μM) with or without IL-6 (20 ng/mL)." (PMID 34922636, 2021).
parasitemia (129 papers, 2010 to 2026). "In T. gondii infection, our findings reported that the parasitic infection caused an augmentation of IL-6 and MIF levels." (PMID 39998112, 2025). "Previous exposure to the parasite can influence the IL-6 and IL-10 response, which is associated with increased parasitemia, reduced maternal weight gain and premature delivery." (PMID 39495782, 2024). "On one hand, IL-6 has been implicated in promoting macrophage differentiation towards the M2 subtype, which is more favorable for chronic parasite infection and increases host susceptibility." (PMID 38655088, 2024). "Parasite density was the principal predictor of the cytokine levels, as parasitemia positively associated with IL‐10, GM‐CSF, IL‐6, IL‐1β, IFN‐ɣ, and TNF‐α, but negatively associated with IL‐3 and TGF‐β." (PMID 39240033, 2024). "None of the cytokine levels were associated with age however, only IL-6 was positively correlate with parasitemia (r = 0.38, p = 0.030)." (PMID 36787308, 2023). "Surprisingly, in our study IL-6 and IL-10 were moderately associated with temperature and only Il-6 was correlated with parasitemia load." (PMID 36787308, 2023). "IL-6 deficiency leads to impaired innate and adaptive immunity to viral, bacterial and parasitic infection." (PMID 33995365, 2021). "These cytokines play an important role in the control of parasite replication; IL-6 deficient animals show higher parasitemia and early mortality." (PMID 34336720, 2021). "The IL6 rs1800795 CG genotype lowered the risk of positive parasitemia (OR = 0.45, 95% CI 0.24–0.86, P = 0.015)." (PMID 33193300, 2020). "Our data support a protective role of IL17A AA, IL18 AA, and IL1B TC genotypes against development/progression of cardiomyopathy and a modulatory effect of the IL6 CG genotype on the risk of parasitemia in Chagas disease." (PMID 33193300, 2020). "The expression levels of other important cytokines associated with N. caninum infection, such as IL-12p40 and IL-6, were modified in placental cells after parasite infection." (PMID 31068227, 2019). "IL-6 is a pro-inflammatory cytokine in the acute innate response after parasite infection and has been implicated as necessary for anti-T." (PMID 30087675, 2018). "By contrast, a reduced APR in association with a significant extension of primary parasitemia is induced in IL-6-deficient mice in response to blood-stage infections." (PMID 25408684, 2014). "We have recently provided evidence from a clinical study that parasitemia, interleukin-10 (IL-10) and interleukin-6 (IL-6) concentration were significantly associated with plasma hepcidin concentration in Kenyan children with acute falciparum malaria." (PMID 24520384, 2014). "Conversely, decreasing IL-6 levels are reported to be associated with decreasing parasitemia and hyperpyrexia, as well as after anti-malarial treatment." (PMID 25408684, 2014). "In a mouse model of cerebral malaria SOCS2−/− mice initially showed reduced parasitemia, however at late stages they showed increased parasitemia associated with increased Th1 and Th17 cells and pro-inflammatory cytokines such as IL-6 and IL-17 with decreased Treg cell activation." (PMID 34604264, 2021). "However, in clinical studies, IL-6 has been found to be associated with hyper-parasitemia and human CM." (PMID 29034874, 2017). "However, high IL-6 levels appear to be part of a generalized acute phase response and do not completely explain the close association of hepcidin concentration and parasitemia." (PMID 24520384, 2014). "It is known that TNF-α promotes the induction of IL-6 and IL-1β; high levels of these cytokines can cause systemic inflammation and the combination of oxidative stress and inflammatory activation is commonly associated to several degenerative processes triggered by parasitosis." (PMID 28177049, 2017).
parasitemia (continued). "Furthermore, cytokines, IL-6, IL-10, and IL-11 stimulate humoral immune responses during parasite infection that could cause differences in expression level of immunoglobulins and humoral immune responses in both fish species during PKD pathogenesis." (PMID 25563603, 2015). "Our results demonstrate that Fer-1 intervention significantly enhances the secretion of pro-inflammatory cytokines including IFN-γ, TNF-α, and IL-6, effectively boosting antimalarial immune effects and reducing parasitemia levels." (PMID 41422632, 2025). "Elevated IL-6 levels are indicative of systemic inflammation and are commonly observed in intracellular parasitic infections titus." (PMID 41150090, 2025). "Previous studies had found that parasitic infections led to an increase in inflammatory factors (IL-3 and IL-6) in sheep." (PMID 40007749, 2025). "Cluster MCODE8 included IL6, CREB1, and HMOX1, which were associated with molecular pathway for oxidative stress (WP5477), parasitic infection pathways (R-HSA-9824443), and leishmania infection (R-HSA-9658195)." (PMID 40528239, 2025). "First, parasite infection can trigger the host immune response and elevate the levels of pro-inflammatory cytokines such as IL-6, TNF-α, and IFN-γ." (PMID 41333290, 2025). "The three primary proinflammatory cytokines associated with parasite infection—IFN-γ, TNF-α, and IL-6—have been identified." (PMID 38521853, 2024). "In individuals with P. vivax infections and high parasitemia, a moderate to strong correlation was observed between IL-6, IL-10, and MCP-1, highlighting the importance of the IL-6/MCP-1/IFN-γ axis in regulating parasitemia in P. vivax infection." (PMID 39567619, 2024). "Cytokines such as gamma interferon (IFN-γ) and interleukin-6 (IL-6) are common activators of inflammatory signaling pathways in the mouse brain in response to parasitic infections." (PMID 38338740, 2024). "IL-6 and IL-10 levels were positively correlated with parasitemia and with total IgG levels; but they were negatively correlated with the gestational age at delivery from Pv-infected woman." (PMID 39495782, 2024). "Taken together, these data are consistent with the H. polygyrus model and indicate that PAC selectively modulates elements of the response elicited by parasitic infection, such as IL-6 production from MLN." (PMID 38944838, 2024). "Children with high parasite density (>10,000 parasites/μL) had higher plasma levels of TNF‐α (p < .001), IFN‐ɣ (p < .001), IL‐1β (p < .001), IL‐6 (p < .001), GM‐CSF (p < .001), and IL‐10 (p < .001) than those with low parasitemia." (PMID 39240033, 2024). "This strategy is based on the rationale that IL-6 acts as a critical pro-inflammatory signal from the host in response to the parasite infection." (PMID 37143657, 2023). "IFN-γ and monocyte chemoattractant protein-1 (MCP-1) production induced in T. cruzi-infected infants correlated with parasitemia, whereas the plasma levels of IL-17A, IL-17F, and IL-6 were less parasite load-dependent." (PMID 38133693, 2023). "The median IL-6 level was between 3- and 4-fold lower in the case of a parasitic infection within the adult group, while an IPI was associated with a higher IL-10/IL-6 ratio." (PMID 35421083, 2022). "It was found that the parasitemia levels and mortality rates were markedly increased when the mice were treated with late IL‐6." (PMID 35635376, 2022). "IL-6 and eotaxin-1 levels are altered among individuals with parasitic infection, suggesting their potential utility in diagnosis." (PMID 35603171, 2022). "We found that the Mapk14ΔM/ΔM mice produced very low levels of IL‐6 at day four p.i. and markedly reduced parasitemia levels." (PMID 35635376, 2022). "Whereas IL-1β was strongly suppressed in PBMC from both uninfected and infected animals receiving BBE, the effect on other cytokines such as IL-6 appeared to be influenced by the parasitic infection, with the suppressive effect less evident in infected pigs." (PMID 35069576, 2021).
parasitemia (continued). "IL-6 is an important cytokine secreted by inflammatory cells and epithelial cells of the lungs against allergens and viral, bacterial and parasitic infections." (PMID 34210332, 2021). "While all mice infected with this large dose developed parasitemia and died, repeatedly infected IL-6 treated mice remained parasite free." (PMID 33329563, 2020). "As for Parasitemia, potential associations were shown with LVEF < 45% (P = 0.031), NYHA score ≥ 2 (P = 0.180), and IL6 rs1800795 heterozygous model (P = 0.023)." (PMID 33193300, 2020). "In conclusion, our findings revealed a novel association between the IL6 −174 C>G SNV and parasitemia in Chagas disease, expressed as a decreased risk of its detection in patients with the CG genotype." (PMID 33193300, 2020). "During parasitemia (day 9) monocytes produced less IL-6 and IL-1β compared to baseline in response to all tested stimuli." (PMID 33324683, 2020). "MSP-9 VLP vaccination also reduced pro-inflammatory cytokine IFN-γ and IL-6 levels and parasitemia, resulting in increased survival time." (PMID 32751598, 2020). "Gao and Pereira reported that T. cruzi infection in animal models and humans produces a high level of IL-6 in serum and tissue, and it is induced during the ascending phase of parasitemia in the acute stage of Chagas disease." (PMID 32455143, 2020). "IgM is involved in the fight against parasitic infection while cytokines, such as IL-6, IL-1β and TNF-α, had an impact on infection processes." (PMID 31882981, 2019). "IL-6 is also involved in host protective response since IL-6-/- mice presented 3-fold higher parasitemia and died earlier than wild-type T. cruzi infected animals, by the subcutaneous route." (PMID 31139194, 2019). "Pyrogenic cytokines such as IL-1β, TNFα, IL-6 and IFNγ were significantly increased in plasma at peak parasitemia when the animals were presenting with clinical illness." (PMID 31536608, 2019). "IL6, together with IL12 and VDR, have been associated with reduced parasitemia, its severity and gametocytemia clearance in P. vivax-exposed individuals." (PMID 29868512, 2018). "All of the cytokines were negatively associated with parasitemia, with the exception of IL-10, TNF-α, and IL-6." (PMID 27418744, 2016). "Parasitemia was significantly correlated with the following cytokines, in order of strength of association: IL-10, IL-12, TNF-α, IFN-γ, IL-1β, IL-6, IL-5, IL-2, IL-4, and IL-7." (PMID 27418744, 2016). "There was a strong positive relationship between blood stream parasitemia and IL-6 (Spearman rho 0.677, P< 0.0001) as well as IL-10 (Spearman rho 0.599, P< 0.0001)." (PMID 26090964, 2015). "NLRP3 and the effector protease caspase-1 appear to participate in controlling the acute phase of T. cruzi infection, as NLRP3−/− and caspase-1−/− mice exhibit a very prominent peak parasitemia, despite their ability to secrete IL-6 and IFN-γ." (PMID 24098823, 2013). "When the infection is not present, Simmental and Modicana cows have higher levels of IL-6 than Holstein, which could indicate an immune system more adapted to parasite infection in these two breeds." (PMID 40302747, 2025). "Moreover, our current results are in line with existing literature that has documented associations between pro-inflammatory cytokines such as IL-6, IL-10 and IFN-γ and parasitemia." (PMID 39407132, 2024). "Different haplotypes of IL6 gene or IL6R genes have been related to IL-6 and other cytokine serum levels in humans, including IL-2, IL-8 and IL-18 cytokines, and with the severity or protective effect of the infectious disease, including parasitic diseases." (PMID 36759910, 2023). "Firstly, during the innate response, T. gondii infection triggers the production of inflammatory cytokines IL-1β, IFNα/β, IL-6, IL-12, IL-15, and IL-18, driving NK cell production of IFNγ, resulting in early control of parasite infection by targeting intracellular parasites." (PMID 37018796, 2023).
parasitemia (continued). "Moreover, Il6–/– mice were sensitive to N67C infections, with respect to parasitemia levels and mortalities, compared to the WT mice." (PMID 35635376, 2022). "Furthermore, like the Tmem173gt and Mb21d1–/‐ mice, the Myd88–/– mice presented a markedly reduced late IL‐6 release and reduced parasitemia levels, thus prolonging their survival." (PMID 35635376, 2022). "Many researchers have emphasized the role of IL-6 in host defense against parasitic infections." (PMID 35286352, 2022). "In addition, a negative correlation was observed between mRNA expression of TLR4, TLR5, IL-6, and parasitemia levels." (PMID 34336720, 2021). "Meanwhile, the concentrations of IL-6 (p<0.001) were higher in children with parasitic infections." (PMID 34539633, 2021). "Furthermore, using a generalized additive model and a likelihood ratio test to determine the impact of parasitemia on the secretion of these cytokines, parasitemia seems to be a major predictor of IL-10 and IL-6 levels." (PMID 33281757, 2020). "Probably denoting that with increasing parasitemia, TNF-α as well as IL-6 may work synergistically to decrease parasitemia levels." (PMID 33281757, 2020). "This original finding raises an enticing mechanistic hypothesis for the relationship between IL6 and parasitemia." (PMID 33193300, 2020). "Also, to determine the impact of parasitemia on these cytokines, we initially determined if parasitemia correlated with any of the cytokines measured and only IL-6 correlated significantly with parasitemia (r = 0.36, p = 0.029)." (PMID 33281757, 2020). "Moreover, rosetting rates were also correlated with parasitemia, IL-6 and IL-10 levels in infected patients." (PMID 33028898, 2020). "It is possible that this mild decrease in the parasitemia levels (18–29%) may be related to temporary and early increases of IL-6 levels as we observed in healthy AWB-treated mice." (PMID 30186314, 2018). "Both IL-6+/+ and IL-6−/− infected mice showed similar levels of parasitemia around 10 d.p.i.." (PMID 28147332, 2017). "In fact, in the later phases of infection, parasitemia and tissue parasitism were significantly reduced in 5-LO−/− mice and it is in accordance with previous studies showing that cytokines such as IL-1β, IL-6, IL-12, TNF-α, and IFN-γ play a relevant role in host killing mechanisms against T. cruzi." (PMID 25165415, 2014). "Furthermore, IL-10 and IL-6 positively correlated with parasitemia in immigrants and travelers, whereas IL-1β only correlated with parasitemia in immigrants, and IL-8 only in travelers." (PMID 23967342, 2013). "IL-10 and IL-6 levels correlated positively with parasitemias in immigrants and travelers." (PMID 23967342, 2013). "In one large study, IL-6 levels in serum were significantly lower in Malian children with hyperparasitemia than those with lower levels of parasitemia, suggesting that IL-6 might be important for control of parasitemia." (PMID 36801374, 2023). "Regarding the expression of genes, stable negative trends connected with parasitic infection are evident for mRNA encoding cytokines in hippocampus, but only for IL-6, traditionally described as a proinflammatory cytokine the reduction in the expression were statistically significant." (PMID 35286352, 2022). "Splenocyte deficiency in IL-6 and/or IFN-γ could also contribute to the establishment of the high parasitic load observed 9 days after infection and/or to the deficit to fully control parasitemia observed in 25% of mice that succumb from the disease." (PMID 34247195, 2021). "It was confirmed that cytokines such as IL-12, TNF-α, IFN-γ, and IL-2 play an important role in controlling the proliferation of Babesia in the early and acute stages of infection, while IL-10, IL-4, IL-5, and IL-6 may involve in chronic and low parasitemia stages of infections." (PMID 32733477, 2020).